FGFR2 (fibroblast growth factor receptor 2)
Diseases named in the same sentence as FGFR2 in open-access papers (continued):
Sharing a sentence is not in itself a finding about the gene and the disease.
breast carcinoma (continued). "GWAS have shown that the SNP haplotype in intron two of FGFR2 is an important risk locus for the development of breast cancer, but they do not address the mechanisms underlying risk association." (PMID 24265722, 2013). "The present findings that FGFR2 is an essential regulator for the maintenance of breast TICs may answer questions, at least in part, in breast cancer." (PMID 23300950, 2013). "We investigated the association between 89 single nucleotide polymorphisms (SNPs) in 7 cytokine/growth-factor genes (FGFR2, IGFBP1, IGFBP3, TGFB1, TNF, VEGF, IL6) and percent MD in 301 premenopausal women (aged 50 to 55 years) participating in the Norwegian Breast Cancer Screening Program." (PMID 23762340, 2013). "However, in our study population FGFR2 expression in male breast cancer was two-fold lower than in female breast cancer." (PMID 23308200, 2013). "We next explored whether FGFR2 might play a role in maintaining a stem-like TIC pool in human breast cancer." (PMID 23300950, 2013). "Data provided by The Consortium of Investigators of Modifiers of BRCA1/2 (CIMBA) indicated that the FGFR2 locus associated with breast cancer in BRCA2 mutation carriers but not in BRCA1 mutation carriers." (PMID 24171766, 2013). "The 10q26.13/FGFR2 rs10736303 (proxy of rs2981579), 5p15.2/ROPN1L rs1092913, 5q12/MRPS30 rs7716600, and 8q24.21 rs1562430 were also confirmed to be associated with breast cancer risk, although the magnitude of the last three SNPs was smaller than that of previous reports." (PMID 22452962, 2012). "Previously, it was known that FGFR2 is amplified and overexpressed in breast cancer." (PMID 21853025, 2011). "Our sample size may have been too small to detect any existing differences, in particular because these differences can be expected to be small, given the mildly increased breast cancer risks conferred by FGFR2 SNPs." (PMID 21767389, 2011). "Early studies have shown expression of FGFR2 only in a minority (4% and 12%) of breast cancers." (PMID 21418638, 2011). "It would be important to consider this when designing new breast cancer treatments that target the FGFR2 signalling pathway, as inhibitors of FGFR2 might, therefore, be expected to have the wrong effect on disease progression." (PMID 21418638, 2011). "High FGF2 and/or FGFR2 protein levels have been correlated with high ER levels in breast cancer." (PMID 21767389, 2011). "Several studies investigating expression of FGFR2 protein in breast cancer seem to contradict the hypothesis that overexpression of FGFR2 is a step in tumour development." (PMID 21418638, 2011). "We can speculate that FGFR2 functions as a tumor suppressor in breast cancer, as well as FGFR4, for which functions are still unknown." (PMID 21108794, 2010). "The lack of association of the SNP in FGFR2 and other breast cancer loci with breast density in this study suggests that some genes influence breast cancer risk independent of breast density." (PMID 18681954, 2008). "In particular, tamoxifen resistance is associated with enhanced glycolysis in ER-positive breast cancer cells through activation of EGFR/MAPK pathway, a pathway also responsible for ligand-independent Erα activation In the MPA-induced tumor model, the FGF-2/FGFR-2 axis drives HI growth." (PMID 35299741, 2022). "In addition to FGFR1 overexpression, aberrant FGFR signaling in breast cancer may also include the amplification of FGFR1 and FGFR2, activation/mutations of FGFR2, increased secretion of FGF2, and other ligands from tumor microenvironment." (PMID 34831231, 2021). "In addition, it was reported that FGFR2 expression is drastically increased in breast cancer." (PMID 32676501, 2020). "In addition to FGFR1, fibroblast growth factor receptor 2 (FGFR2 gene, chromosome 10) and fibroblast growth factor receptor 3 (FGFR3 gene, chromosome 4) belong to the same family of receptor tyrosine kinases and are linked to breast cancer susceptibility." (PMID 32852708, 2020).
breast carcinoma (continued). "Indeed, two regulatory polymorphisms (rSNPs), rs2981578 in the fibroblast growth factor receptor 2 (FGFR2) gene and rs554219 in the CCND1 gene may be causally related to breast cancer risk." (PMID 30823486, 2019). "For instance, the Gene Ontology pathway Ear Morphogenesis includes FGFR2 and is ranked among the top 100 most significant gene sets, but as we will show later, the same pathway defined without FGFR2 possesses minimal association with breast cancer." (PMID 30875371, 2019). "Aberrant expression of FGFR2 can contribute to the proliferation of some malignant cancers such as gastric cancer, prostate cancer and esophageal carcinoma and facilitates cell survival in many different cancers including prostate cancer, breast cancer, and gastric cancer." (PMID 26011628, 2015). "Though, none of them has reached the clinical phase as yet and there are many hurdles to be overcome, there is enough encouraging evidence suggesting that targeting FGFR2 along with other FGFRs in certain subtypes of breast cancer could be a valuable approach in the future." (PMID 25333473, 2014). "It is possible that Clims may in part promote breast cancer through activation of Fgfr2 expression." (PMID 25079073, 2014). "Since a previous report from South India did not succeed in replicating the association of the studied FGFR2 variant with breast cancer, as was observed in Europeans and other Asian populations, it was relevant to revisit the region along with other SNPs from the same LD block." (PMID 25333473, 2014). "Indeed, FGFR2 is amplified and overexpressed in 4–12% of human breast cancers." (PMID 23300950, 2013). "FGFR2 also may play an important role in human breast cancer." (PMID 23300950, 2013). "For example, the gene for fibroblast growth factor receptor 2, FGFR2, harbours variants associated with breast but not ovarian cancer and breast cancer-associated variants in this gene appear to regulate the transcriptional activation of FGFR2 in an estrogen-dependent manner." (PMID 24025454, 2013). "Moreover, FGFR2 has been recognized among the five most prominent candidate susceptibility genes in non-hereditary breast cancer." (PMID 23185502, 2012). "To address whether FGFR2 expression levels in skin fibroblasts correlated to those in breast fibroblasts, we cultured fibroblasts from the skin tissue as well as the normal breast tissue from 22 breast cancer patients." (PMID 21767389, 2011). "Researchers screened a panel of 51 breast cancer cell lines and identified two cell lines, MFM223 and SUM52PE, that exhibited FGFR2 gene amplification and protein overexpression." (PMID 41318657, 2025). "FGF-2 and medroxyprogesterone acetate (MPA) stimulation prompted the colocalization of FGFR-2, PR, and STAT5 in the nuclei of breast cancer cells." (PMID 40507264, 2025). "These targets (FGFR2, PTLH, ELL, and ZMIZ1) have already been identified through meta-GWAS of breast cancer." (PMID 40938940, 2025). "Recently, a study demonstrated that fibroblast growth factor receptor 2 (FGFR-2) interacts with progesterone receptor (PR) and STAT5 in hormone receptor-positive T47D breast cancer cells and in breast cancer patient samples." (PMID 40507264, 2025). "Our in vitro validation showed that Rad51b deletion affects the expression of ERα in mouse Fgfr2-mutant HP5008 cells, Brca1-mutant 545 cells, and the human breast cancer MCF-7 cells." (PMID 41318657, 2025). "Using publicly available data, we found a higher gene expression of FGFR2 in the less aggressive luminal cancers, and a lower gene expression in HER2-positive breast cancers." (PMID 39596875, 2024).
breast carcinoma (continued). "FGFR2 levels have been found to be amplified and overexpressed in lapatinib-resistant HER2-positive breast cancer cells." (PMID 39596875, 2024). "This kinome reprogramming involved RTKs including FGFR2, ERBB2 and MET that were heterogeneously upregulated in different HER2+ breast cancer cell lines growing in the presence of lapatinib." (PMID 39513002, 2024). "This review explores the structure, signaling pathways, and implications of FGFRs, particularly FGFR1, FGFR2, FGFR3, and FGFR4, in ER+ breast cancer." (PMID 39040443, 2024). "Dovitinib was investigated in combination with fulvestrant in postmenopausal women with hormone receptor (HR)-positive, HER2-negative, FGFR (FGFR1, FGFR2, or FGF3)-amplified breast cancer who progressed on endocrine therapy in a phase II trial." (PMID 38255923, 2024). "Furthermore, the authors showed that FGF5 secreted by cancer-associated fibroblasts (CAF) in the microenvironment might be responsible for the high activation of FGFR2 on the neighboring epithelial cells, confirming the potential signaling switch between HER2 and FGFR2 in breast cancer." (PMID 38139837, 2023). "The role of fibroblast growth factor receptor 2 (FGFR2), an important mediator of stromal paracrine and autocrine signals, in mammary gland morphogenesis and breast cancer has been extensively studied over the last years." (PMID 37191822, 2023). "Since breast cancer progression is closely linked to EGFR tyrosine kinase signal; it can be speculated that diosgenin-mediated Rap1 signal could attenuate tumor invasion and metastasis; was observed to be modulated via the modulation of three genes i.e., PDGFRB, IGF1R, and FGFR2." (PMID 36686654, 2022). "An idea that is worth exploring would be the combination of FGFR2 and EGFR inhibitors, based on the reciprocal regulation of these two RTKs in breast cancer cells in vitro." (PMID 35193394, 2022). "For instance, the amplification of FGFR2 results in the activation of PI3K–AKT signalling and inhibition of apoptosis in breast cancer cell lines." (PMID 35193394, 2022). "The genes involved in the known three loci—FGFR2, CCND1 and TOX3—have been thoroughly discussed in relation to breast cancer." (PMID 35267517, 2022). "In conclusion, FGFR2, RET, ERBB4, MMP16, FN1, and SOX2 are potential targets of HON for overcoming TAM resistance in breast cancer." (PMID 36601474, 2022). "Taken together, FGFR2, RET, and ERBB4 are potential targets of HON for overcoming ER+ breast cancer resistance to TAM." (PMID 36601474, 2022). "FGF4 promotes resistance to lapatinib in HER2-positive breast cancer cell lines through FGFR1 signalling, and FGF5 by inducing FGFR2 activation, which in turns transactivates HER2 and promotes resistance." (PMID 35193394, 2022). "Six target genes (FGFR2, RET, ERBB4, SOX2, FN1, and MMP16) were analyzed across breast cancer studies using the cBioPortal to assess genomic alterations." (PMID 36601474, 2022). "In breast cancers, the most prevalent fusion genes were FGFR family genes (total, 0.48%; FGFR2, 0.34%; FGFR1, 0.14%), ErbB family genes (total, 0.47%; EGFR, 0.20%; ERBB2, 0.27%), ALK (0.27%) and ROS1 (0.07%)." (PMID 36369474, 2022). "In fact, both SConES GS and GM selected chromosome regions related to breast cancer, like 3p24 (SLC4A7/NEK10), 5p12 (FGF10, MRPS30), 10q26 (FGFR2), and 16q12 (TOX3)." (PMID 33735170, 2021). "In HER-positive breast cancer, the secretion of FGF5 by CAFs leads to FGFR2 activation in cancer cells and acquisition of resistance to trastuzumab and lapatinib (EGFR/HER2 inhibitors) through FGFR2/c-Src-mediated HER2 transactivation." (PMID 34830951, 2021).
breast carcinoma (continued). "In breast cancer patients, FGFR4 and FGFR2 SNPs were previously suggested to be candidate pharmacogenomic factors to predict the response to chemotherapy." (PMID 34830836, 2021). "Other studies showed that amplification of FGFR1, FGFR2, or FGFR3 in ER-positive human breast cancers correlates with concomitant resistance to estrogen-related therapy." (PMID 34830951, 2021). "BGJ398, a highly potent and selective pan-FGFR kinase inhibitor in clinical trials, has demonstrated antitumor activity in advanced cholangiocarcinoma patients with FGFR2 alterations and promoted tumor reductions in FGFR1-amplified breast cancer patients." (PMID 31987043, 2020). "FGFR2 amplification is also a common FGFR aberration, occurring in 5–10% of breast cancers and 4% of TNBCs, and FGFR2 signaling drives resistance to Tamoxifen in ER+ disease." (PMID 31987043, 2020). "Besides this, the release of FGF7 by CAFs and its interaction with the cognate receptor FGFR2 have been shown to induce ER phosphorylation, ubiquitination, and subsequent proteasomal degradation, therefore counteracting the endocrine treatment in breast cancer cells." (PMID 33081025, 2020). "We found weak evidence for the association of risk variants rs294174 (ESR1), rs16886165 (MAP3K1), rs2214681 (CNTNAP2), rs4237855 (VDR), rs9594579 (RANKL), rs8183919 (PTGIS), rs2981582 (FGFR2), and rs1799950 (BRCA1) with sporadic breast cancer." (PMID 33126731, 2020). "Fibroblast growth factor receptor-2 (FGFR2) is an emerging histologic marker in several cancers, including breast carcinoma (BCa)." (PMID 33297384, 2020). "Various aberrations in the fibroblast growth factor receptor genes FGFR1, FGFR2, and FGFR3 are found in different cancers, including breast cancer (BC)." (PMID 32852708, 2020). "This study investigated the amplification rates of the fibroblast growth factor receptor genes FGFR1, FGFR2, and FGFR3 in patients with breast cancer." (PMID 32852708, 2020). "The aim of this study was to investigate the amplification rates of FGFR1, FGFR2, and FGFR3 in patients with breast cancer and their impact on prognosis." (PMID 32852708, 2020). "There is amplification of FGFR1 and FGFR2 in ER+ breast cancer and TNBC, respectively, and FGFR1 amplification was noted as an independent factor to predict the overall survival in ER + breast cancer." (PMID 31754359, 2019). "Amplifications of FGFR2 and FGFR4 are rarer, observed in less than 1 and 2.3% of breast cancer patients, respectively." (PMID 31142340, 2019). "Published response rates were 33% in FGFR2 amplified gastroesophageal cancer and 12.5% in FGFR1 amplified breast cancer." (PMID 30181810, 2018). "Anti-tumor effects were also recognized in cholangiocarcinoma harboring a FGFR2 fusion and in FGFR1 amplified breast cancer." (PMID 30181810, 2018). "The nominally significant SNPs included colorectal cancer GWAS SNPs in SMAD7, C11orf93, SCG5, and ATF1, and breast cancer SNPs related to CDKN2B-AS1, FGFR2, GDI2, CDYL2." (PMID 29698419, 2018). "The conversion between FGFR2 (IIIb) and FGFR2 (IIIc) are closely connected with EMT and MET (mesenchymal-epithelial transition) of breast cancer cells." (PMID 28881705, 2017). "Dovitinib (TKI258), a small-molecule inhibitor of FGFR1, FGFR2, and FGFR3 and other receptor tyrosine kinases, has shown preclinical activity in FGFR-expressing breast cancer models in vivo and in vitro." (PMID 28183331, 2017).
breast carcinoma (continued). "As a follow-on from our previous study demonstrating that FGFR2 activates RSK2 in BCa cells in vitro, herein we have undertaken an evaluation of a potential clinical significance of an interaction between FGFR2 and RSK2 in breast cancer." (PMID 27476168, 2016). "We have recently demonstrated that, fibroblast growth factor 2 (FGFR2), signalling via ribosomal S6 kinase 2 (RSK2), promotes progression of breast cancer (BCa)." (PMID 27852068, 2016). "Herein we showed for the first time that in MCF7, T47D and BT474 breast cancer cell lines, phosphorylation of PR at Ser294 and subsequent downregulation of PR protein level was induced by FGF7/FGFR2 (fibroblast growth receptor 2)-triggered signalling." (PMID 27852068, 2016). "We demonstrated that FGFR2, RSK2 and RSK-P were expressed in breast cancer tissue and that patients with tumours devoid of RSK-P alone or in combination with FGFR2 had longer disease-free survival." (PMID 27476168, 2016). "A cross-talk between FGFR2 and PR signalling and a nuclear interaction between FGFR-2 and PR in breast cancer cells have already been reported." (PMID 27852068, 2016). "Evaluation of cellular effects of the cross-talk between FGF7/FGFR2 and PR revealed that FGF7 or Pg, tested separately, stimulated anchorage-independent growth and migration of breast cancer cells." (PMID 27852068, 2016). "FGFR2 and BCL2 were again selected in this dataset confirming the strong relevance of the two genes in breast cancer." (PMID 27378931, 2016). "Herein, we have undertaken an evaluation of a possible relationship between FGFR2/RSK2 interdependence and disease outcome in breast cancer (BCa) patients." (PMID 27476168, 2016). "These genes include TP63 for bladder cancer, FGFR2 and MAP3K1 for breast cancer, HNF1B for ovarian cancer, KLK3 for prostate cancer, and CDKN2A for skin cancer." (PMID 26374197, 2015). "FGFR2, the second most commonly amplified gene of the FGFR family, has been shown to be amplified in gastric cancer, breast cancer, and non-small-cell lung cancer." (PMID 25171497, 2014). "In our study population of 133 cases of male breast cancer, we found 4 cases (3.0%) expressing HER2, 15 cases (11.4%) EGFR, 6 cases (4.5%) MET, 16 cases (12.1%) FGFR2, and 50 cases (38.5%) IGF1-R." (PMID 23308200, 2013). "We also performed MLPA analysis to detect copy number variations in FGFR2 and FGF10 in breast tissue of 50 sporadic breast cancer patients." (PMID 23527311, 2013). "We found that expression of IGF1-R was present in 38.5%, FGFR2 in 12.1%, EGFR in 11.4%, HER2 in 3.0%, and MET in 4.5% of male breast cancers." (PMID 23308200, 2013). "Compared to female breast cancer, IGF1-R and carbonic anhydrase 12 (CAXII) were more frequently and CD44v6, MET and FGFR2 less frequently expressed in male breast cancer." (PMID 23308200, 2013). "A potential panel of markers for molecular imaging, consisting of EGFR, IGF1-R, FGFR2, CD44v6, CAXII, GLUT1, and CD44v6 was positive in 77% of male breast cancers, comparable to female breast cancers." (PMID 23308200, 2013). "In conclusion, we found that expression of individual growth factor receptors (IGF1-R, FGFR2, and MET) and CD44v6, CAXII in male breast cancer is different compared to female breast cancer." (PMID 23308200, 2013). "Both breast cancer mutants led to an increased tyrosine phosphorylation of FRS2, a well-characterized FGFR2 substrate, as revealed by immunoblotting with anti-p-FRS2 antibody after SDS-PAGE." (PMID 23527311, 2013). "Ten of the 11 breast cancer susceptibility loci reported by consortia also showed associations in our predominantly Caucasian study population, and the associations were independent of BMI; four FGFR2 SNPs and TNRC9-rs3803662 were among the most notable associations." (PMID 23717390, 2013). "Overexpression of FGFR2, a receptor for FGF, has been demonstrated in several types of neoplasia, including breast cancer, prostate cancer, renal cell carcinoma, and gastric cancer." (PMID 22355249, 2012).